NR3C2 (nuclear receptor subfamily 3 group C member 2)
Description:
Receptor for both mineralocorticoids (MC) such as aldosterone and glucocorticoids (GC) such as corticosterone or cortisol. Binds to mineralocorticoid response elements (MRE) and transactivates target genes. The effect of MC is to increase ion and water transport and thus raise extracellular fluid volume and blood pressure and lower potassium levels.
Synonyms: MR; MCR; MLR; NR3C2VIT
Tractability: Small molecule: an approved drug acts on it; a structure with a bound ligand is known; a high-quality ligand is known; it has a binding pocket of medium quality; it belongs to a druggable protein family. Antibody: UniProt places it where antibodies can reach, with medium confidence. PROTAC: ubiquitination databases record sites on it; a small molecule that binds it is known.
Target class: Nuclear receptor; Nuclear hormone receptor subfamily 3; Nuclear hormone receptor subfamily 3 group C; Transcription factor; Nuclear hormone receptor subfamily 3 group C member 2
Chemical probes: ALDOSTERONE (high quality), PF-03882845 (high quality)
Gene: Protein-coding gene on chromosome 4 (148,078,762 to 148,445,549, reverse strand). Ensembl gene ENSG00000151623.
Subcellular location: Cytoplasm; Nucleus; Endoplasmic reticulum membrane
Subcellular location (Human Protein Atlas): Nucleoplasm
Pathways (Reactome):
Cellular responses to stimuli: HSP90 chaperone cycle for steroid hormone receptors (SHR) in the presence of ligand
Gene expression (Transcription): Nuclear Receptor transcription pathway
Metabolism of proteins: SUMOylation of intracellular receptors
Gene Ontology:
Molecular function: protein binding; sequence-specific double-stranded DNA binding; TBP-class protein binding; DNA-binding transcription factor activity; DNA-binding transcription factor activity, RNA polymerase II-specific; estrogen response element binding; nuclear receptor activity; nuclear steroid receptor activity; sequence-specific DNA binding; zinc ion binding
Biological process: positive regulation of non-canonical NF-kappaB signal transduction; nuclear receptor-mediated steroid hormone signaling pathway; regulation of transcription by RNA polymerase II; signal transduction; regulation of DNA-templated transcription
Cellular component: nucleoplasm; receptor complex; chromatin; cytosol; nucleus; cytoplasm; endoplasmic reticulum membrane
Genetic constraint (gnomAD): Loss-of-function variants: 15 observed, 86.07 expected, observed/expected ratio (o/e) 0.17, 90% interval 0.12 to 0.27. The upper end of that interval is the gene's LOEUF score, 0.27, which puts it in group 1 of 6, group 1 being the genes least tolerant of losing a copy. Missense variants: 956 observed, 1,245.8 expected, observed/expected ratio (o/e) 0.77, 90% interval 0.73 to 0.81. Synonymous variants: 455 observed, 473.97 expected, observed/expected ratio (o/e) 0.96, 90% interval 0.89 to 1.04.
Gene-disease validity (ClinGen):
ClinGen rates the evidence that NR3C2 causes each of these diseases.
autosomal dominant pseudohypoaldosteronism type 1 (autosomal dominant): Definitive. Renal pseudohypoaldosteronism type 1 (renal PHA1) is a mild form of primary mineralocorticoid resistance restricted to the kidney.
pseudohyperaldosteronism type 2 (autosomal dominant): Limited.
Homologues: Orthologues: chimpanzee NR3C2 (99% identical), macaque NR3C2 (99% identical), rabbit NR3C2 (95% identical), pig NR3C2 (95% identical), dog NR3C2 (94% identical), guinea pig NR3C2 (91% identical), mouse Nr3c2 (91% identical), rat Nr3c2 (90% identical), tropical clawed frog nr3c2 (68% identical), zebrafish nr3c2 (52% identical), Drosophila melanogaster ERR (11% identical). Paralogues in human: NR3C1 (30% identical), PGR (29% identical), AR (27% identical), ESR2 (13% identical), ESRRG (13% identical), ESRRB (12% identical), ESRRA (12% identical), ESR1 (12% identical).
Diseases named in the same sentence as NR3C2 in open-access papers:
NR3C2 is named in the same sentence as 393 diseases in open-access papers, as found by Europe PMC text mining. Sharing a sentence is not in itself a finding about the gene and the disease. The quoted sentences say what the papers report.
Hypertension (333 papers, 2005 to 2026). The presence of chronic increased pressure in the systemic arterial system. "The patient was diagnosed with hypertension, hyperkalemia, and a Pro701Leu mutation in the NR3C2 gene." (PMID 40441250, 2025). "This case report documents the first known instance of the Pro701Leu missense mutation in the NR3C2 gene, emphasizing its significant role in the pathophysiology of hypertension and hyperkalemia." (PMID 40441250, 2025). "Functional polymorphisms of NR3C2 have been associated with early-onset hypertension in a Spanish population study and pregnancy-exacerbated early-onset hypertension with down regulation of MR in maternal mononuclear leucocytes." (PMID 41444673, 2025). "This case report describes the clinical features of a previously undocumented NR3C2 mutation, Pro701Leu, in a 60-year-old man presenting with hypertension and hyperkalemia." (PMID 40441250, 2025). "For instance, mutations in the CACNA1D (primary aldosteronism) and NR3C2 (Geller syndrome) genes are known causes of monogenic hypertension." (PMID 37059828, 2023). "Several genes, including CYP17A1, CYP11B2, HSD11B1, CYP11B1, and NR3C2, which are implicated in the control of hypertension, regulate the synthesis of steroid hormones, such as glucocorticoids, mineralocorticoids, androgens, and estrogens." (PMID 37571339, 2023). "As a result, three variants (rs11737660, rs6810951 and rs10519963) in NR3C2 were associated with both blood pressure and hypertension." (PMID 34067580, 2021). "According to studies, specific NR3C2 gene variants may have a role in the emergence of hypertension." (PMID 37571339, 2023). "Overactivation of nuclear receptor subfamily 3 group C member 2 (Nr3c2; also known as mineralocorticoid receptor or MR) aggravates cardiovascular diseases, including hypertension, atherosclerosis, and MI." (PMID 37018396, 2023). "The finding that the gene collapsing analyses in essential hypertension identified variation in genes (PKD1, PKD2, COL4A4, UMOD, CACNA1D, and NR3C2) that are possible causes of undiagnosed secondary hypertension is worthy a special comment." (PMID 37059828, 2023). "Spironolactone is an essential drug to treat resistance hypertension by acting on mineralocorticoid receptor (MR) NR3C2." (PMID 36438559, 2022). "We found CpGs previously associated with hypertension and kidney function to be associated with concentrations of renin and aldosterone, and we found one DMP annotated to the NR3C2 gene of the RAAS system to be associated with ARR." (PMID 36457109, 2022). "We find that hydrochlorothiazide targets the sodium-chloride symporter pathway (e.g., SLC12A3) and spironolactone targets the mineralocorticoid receptor pathway (e.g., NR3C2), both in the hypertension disease module following by the Complementary Exposure category." (PMID 30867426, 2019). "To test this hypothesis, we screened hypertension candidate genes for putative miRNA target sites and experimentally verified the mineralocorticoid receptor NR3C2 as a target for miR-124 and miR-135a." (PMID 19944075, 2010). "Another form is Geller syndrome due to a specific variant in NR3C2 which conveys agonism rather than antagonism of the mineralocorticoid receptor by progesterone and other steroid hormones thus resulting in early-onset hypertension that is aggravated in pregnancy." (PMID 35585366, 2023). "In fact, one of the first few high-throughput genotyping was performed on only genes underlying monogenic hypertension and hypotension (not genome-wide) which found two renal sodium regulatory genes (KCNJ1 and NR3C2) to have SNPs associated with blood pressure in the general population." (PMID 29666641, 2018). "Moreover, some but not all studies of vessels from EC-MR KO mice in models of hypertension or endothelial dysfunction show a decreased contractility in response to constrictors, in line with a protective effect of Nr3c2 gene ablation in endothelial cells." (PMID 29466427, 2018).
diabetes (136 papers, 2011 to 2026). "They found several novel NR3C2 polymorphisms associated with an increased risk of PCOS in the diabetes-prone participants." (PMID 41010358, 2025). "Polymorphisms of genes involved in diabetes pathogenesis, including IL8RA, TXN, NR3C2, COX5A, and GCLC, significantly modulated the association between urinary As levels and the odds of diabetes in a general Spanish population." (PMID 37624175, 2023).
Obesity (97 papers, 2013 to 2026). Accumulation of substantial excess body fat. "In the post-HCT group we found significantly lower expression of AGTR2, FLJ32810, NR3C2 and TMEM133 genes, and significantly higher expression of BAT2D1, MOV10, PIK3CG and WNK1 genes compared with the obesity control group." (PMID 33927307, 2021).
depression (61 papers, 2007 to 2026). "DNA methylation of NR3C1 and NR3C2 were measured in placental and infant buccal samples, and it is found that maternal early pregnancy depressive disorder and symptoms were associated with lower DNA methylation at NR3C2 CpG_24 in placental tissue." (PMID 33015076, 2020). "Furthermore, various polymorphisms and haplotypes of the MR gene (NR3 C2) have been linked to depression." (PMID 40281288, 2025). "Depressed patients exhibit decreased mineralocorticoid receptor (MR) expression in the hippocampus and prefrontal cortex, and several polymorphisms and haplotypes of the MR gene (NR3C2) have been associated with depression." (PMID 39962033, 2025). "Emotional processing biases have been associated with several depression candidate genes, such as the 5-HTTLPR polymorphism in the SLC6A4 gene, and the BDNF, COMT and NR3C2 genes." (PMID 25379724, 2014). "This indicates that the NR3C2 gene may interact with early - life stress to influence the development of adolescent depression in a sex - specific manner." (PMID 40406494, 2025). "Specifically, we investigated the genetic and epigenetic correlates of key stress-associated genes (NR3C1, NR3C2, FKBP5, GILZ, SLC6A4) with psychological characteristics (depression, anxiety, and stress) often included in DD diagnostic criteria, as well as with brain EEG findings." (PMID 38391714, 2024). "The expression level of the 5-HT1A, DRD1, ADRA-2A, GABA-A α1, CNR1, NR3C2, NOD1, NLRP3 and MC4R; BDNF levels, glial activity and intestinal permeability were determined in chronic stress-induced depression in rats." (PMID 40281288, 2025). "Some studies have also reported other genes, such as the mineralocorticoid receptor gene (NR3C2), the promotor of serotonin transporter gene (SLC6A4), and FK506-binding protein 5 (FKBP5) with ELS and depression." (PMID 36517640, 2023). "A recent study examining sex differences in pleiotropic effects for depression and smoking found pleiotropic effects of FKBP5 on depression and smoking initiation among all participants and pleiotropy for NR3C2 and CHRNA5 for depression and cigarettes per day among females." (PMID 38790194, 2024). "In our regression analysis of depressed patients only, we did find that medication use led to differences in expression when controlling for age, depression severity, and diagnosis, including increased expression of ASIC receptors, transcription factor NR3C2, and growth factor APP." (PMID 24143878, 2013). "Also in a study conducted on a group of early school-age children who were diagnosed with depression in the prenatal period, a reduced methylation of the glucocorticoid receptor (NR3C1) gene, mineralocorticoid receptor (NR3C2) gene and the serotonin receptor (SLC6A4) gene were indicated." (PMID 33385173, 2021). "NR3C2 codes for mineralocorticoid receptor 1 (MR1) and antidepressants were shown to modulate MR hormone-binding and expression in the context of the corticosteroid receptor hypothesis of depression." (PMID 27091189, 2016). "Memory bias may not be strongly associated with the PCLO rs2522833 polymorphism, unlike other genes that have been associated with depression (e.g. BDNF, NR3C2)." (PMID 25379724, 2014).
myocardial infarction (59 papers, 2013 to 2025). Gross necrosis of the myocardium, as a result of interruption of the blood supply to the area, as in coronary thrombosis. "Prior studies reported an association between the presence of NR3C2 single-nucleotide polymorphisms (SNPs) and an increased cortisol production during a stress response such as acute myocardial infarction (AMI), which may lead to adverse cardiac remodeling." (PMID 36612333, 2022).
Anxiety (53 papers, 2007 to 2026). Intense feelings of nervousness, tension, or panic often arise in response to interpersonal stresses. "In addition, we evaluated the expression of stress-related genes: glucocorticoid and mineralocorticoid receptors (Nr3c1 and Nr3c2) and Nr1d1, which encodes a transcription factor (also known as REVERBα) modulating sociability and anxiety-related behavior." (PMID 32190129, 2020). "The nr3c2 gene encodes the mineralocorticoid receptor, which is involved in the regulation of HPA axis activity and is associated with anxiety and stress behaviors." (PMID 40243462, 2025). "We hypothesized that ELS would disrupt normative development in both generations, manifesting as altered methylation and expression of genes associated with stress signaling pathways (Nr3c1, Nr3c2, and Bdnf), blunted corticosterone (CORT), and anxiety-like behaviors." (PMID 31143105, 2019). "Finally, while no significant changes in anxiety-like behaviours were observed in this study, several genes associated with anxiety, such as CRHR1, NR3C1, NR3C2, were altered in a region and time dependent manner injured mice." (PMID 40375338, 2025).
metabolic syndrome (31 papers, 2012 to 2025). A cluster of metabolic risk factors for CARDIOVASCULAR DISEASES and TYPE 2 DIABETES MELLITUS. "Adipocyte-specific overexpression of NR3C2 exacerbates metabolic syndrome in mice." (PMID 36585686, 2022).
breast carcinoma (22 papers, 2013 to 2025). "In polarized epithelial cells, its primary target is the ligand aldosterone, NR3C2 is also involved in the development of various tumor cells, including pancreatic ductal adenocarcinoma, hepatocellular carcinoma, and breast cancer." (PMID 40229278, 2025). "MiR-301b exerted tumor-promoting effects through co-regulation with its target gene NR3C2 in breast cancer MCF7 and BCAP-37 cells." (PMID 37508580, 2023). "This identified thirty-one unique genes, of which five have previously been associated with breast cancer (LGR6, NR3C2, LOC105377563, CTNNA3, PRIM1)." (PMID 37345113, 2023). "NR3C2 was validated as a direct target of miR-301b-3p via bioinformatics analysis and dual-luciferase reporter assay, and NR3C2 was downregulated in breast cancer cell lines." (PMID 33542733, 2021). "TNBC cells' downregulation of NR3C2 by siRNA resulted in significant decrease of the breast cancer stem cell marker CD44 levels." (PMID 34737698, 2021). "In this study, we used the TCGA–BRCA data set to analyze the correlation between the expression of NR3C2 and the OS in patients with breast cancer." (PMID 34737698, 2021). "Overexpression NR3C2 could repress the proliferation, migration, and invasion for breast cancer and hepatocellular carcinoma." (PMID 35619698, 2022). "The results show that a high expression of NR3C2 in patients with breast cancer in all stages could improve the survival probability." (PMID 34737698, 2021). "In addition, NR3C2 can suppress cell development and is a prognostic target in breast cancer." (PMID 39770478, 2024). "However, there are few studies about the relationship between NR3C2 and breast cancer." (PMID 34737698, 2021). "The mineralocorticoid receptor (MR, NR3C2) is another receptor of interest, given that it is most likely expressed in the majority of breast cancers (up to 90%)." (PMID 34638457, 2021). "However, the clinical significance of NR3C2 in breast cancer remains unclear." (PMID 33564687, 2021).
COVID-19 (17 papers, 2020 to 2026). A disease caused by infection with severe acute respiratory syndrome coronavirus 2. "NR3C2 is a gene involved in the regulation of sodium levels and therefore blood pressure which may confer susceptibility and severity of cardiovascular complications seen in patients with COVID-19." (PMID 33924631, 2021). "The NR3C2 activity of corticosteroids, and indeed the other targets including progesterone receptors, may well be beneficial for other aspects of COVID-19 severity mitigation beyond the IL-6 cytokine nexus that was explored in this study via clinical-omics triangulation." (PMID 33723251, 2021).
pancreatic cancer (15 papers, 2019 to 2025). "Over-expression of MIF induced a marked increase of miR-301b and reduction of NR3C2 levels, resulting in profound proliferation, migration, and invasion of pancreatic cancer cell lines (PANC-1 and Capan-2)." (PMID 33776775, 2021). "NR3C2 (nuclear receptor subfamily, 3; group C member, 2) is a known tumor suppressor, and its expression was found to be reduced in colon carcinoma, clear-cell renal cell carcinoma, and pancreatic cancer." (PMID 34249704, 2021). "A lower expression of NR3C2 was suggested to be related to an increase in angiogenesis in early stage cervical carcinoma and poor prognosis in pancreatic cancer patients." (PMID 34737698, 2021). "Later, some studies have revealed the tumor-suppressive role of NR3C2 in cancer progression, such as in pancreatic cancer and clear cell renal cell carcinoma." (PMID 32280303, 2020). "Conversely, miR-135b-5p promotes migration, invasion and EMT of pancreatic cancer cell by targeting NR3C2 as an oncogene, and overexpression of miR-135b-5p leads to poor prognosis." (PMID 31510100, 2019). "JUN interacts with NR3C2 to modulate glycolysis in pancreatic cancer." (PMID 40332792, 2025). "Previous studies have shown that the expression of NR3C2 can be downregulated by miR-135b-5p, miR-766, miR-454, and miR-1204 in pancreatic cancer, liver cancer, oral squamous cell carcinoma, and glioblastoma, respectively, thereby promoting the malignant phenotype of tumor cells in above cancers." (PMID 33564687, 2021). "Functional analysis showed that NR3C2 may inhibit pancreatic cancer cell metastasis by reducing EMT, with an induction in E-cadherin and a decrease in ZEB1, N-cadherin, and vimentin." (PMID 34249704, 2021). "In addition, NR3C2 has been reported as a tumor suppressor gene in clear cell renal cell carcinoma, pancreatic cancer, liver cancer, colon adenocarcinoma, oral squamous cell carcinoma, and glioblastoma cancer." (PMID 33564687, 2021). "Also, the tumor-suppressive role of NR3C2 has been validated in pancreatic cancer and clear cell renal cell carcinoma." (PMID 32280303, 2020). "The relationship between mir-301b and NR3C2 has also been validated in pancreatic cancer." (PMID 30755833, 2019). "In addition, patients with low levels of NR3C2 have a poor prognosis in pancreatic cancer and renal cell carcinoma." (PMID 30755833, 2019).
Cognitive impairment (12 papers, 2011 to 2025). Abnormal cognition is characterized by deficits in thinking, reasoning, or remembering. "Genetic variations in the GR-encoding gene NR3C1 and mineralocorticoid receptor (MR)-encoding gene NR3C2 have been manifested in both bioinformatics and clinical studies to correlate with increased risks of cognitive impairments and HPA axis dysregulation." (PMID 38012702, 2023). "miR-135b-5p upregulation can reduce neuronal damage and inflammatory response in PSCI by targeting NR3C2, which is useful for poststroke cognitive impairment treatment." (PMID 36593772, 2022).